MMP3 (matrix metallopeptidase 3)
Diseases named in the same sentence as MMP3 in open-access papers (continued):
Sharing a sentence is not in itself a finding about the gene and the disease.
tendinopathy (30 papers, 2011 to 2025). "We selected the MMP3 gene for this study due to numerous associations of its polymorphisms with the risk of tendinopathy and changes in its expression during tendon damage." (PMID 41226619, 2025). "As for the MMP3 gene, G allele (rs679620) causes its overexpression, generating scenarios such as an increased risk of tendinopathy." (PMID 39882103, 2025). "In summary, high-performance athletes with TNC-rs2104772-A have a higher risk of developing tendinopathy, while MMP3-rs591058-T is associated with an increased risk of having more episodes of tendinopathy manifestations." (PMID 39594135, 2024). "The TNC-rs2104772-A allele was significantly associated with tendinopathy (OR: 1.4; 95% CI: 1.1–1.8), while athletes carrying the MMP3-rs591058-T allele were linked to an increased risk of more episodes of disease manifestation (OR: 1.7; 95% CI: 1.1–2.8)." (PMID 39594135, 2024). "Moreover, several single nucleotide polymorphisms (SNPs) of the MMP3 gene showed association with the risk of tendinopathy, including rs679620 and rs591058." (PMID 41226619, 2025). "This indicates that, although MMP3 is associated with the pathogenesis of tendinopathy, and polymorphisms in this gene are associated with the risk of its occurrence, this does not translate into an association with the effectiveness of tendinopathy treatment using platelet-rich plasma." (PMID 41226619, 2025). "The same genotypes are also related to a higher risk of tendinopathy, which may be caused by reduced MMP3 remodeling activity." (PMID 41226619, 2025). "Brisk and colleagues observed that the rs591058-TT genotype, along with the contribution of the T allele on the haplotype with two other SNPs of MMP3 (rs650108 and rs679620), indicated a predisposition to tendinopathies in high-level Croatian athletes, which is consistent with our findings." (PMID 39594135, 2024). "In addition, this study observed that the presence of the MMP3-rs591058-T allele was associated with a four-fold increased risk of the occurrence of more episodes of tendinopathy manifestations." (PMID 39594135, 2024). "A study also suggested that the expression of MMP-3 is suppressed during tendinopathy, and MMP-3 polymorphism may contribute to chronic tendon disorders." (PMID 38247510, 2024). "In addition, the MMP-3 rs679620 variant has been shown to interact with the COL5A1 rs12722 variant to modify the risk of tendinopathy." (PMID 29108328, 2017). "Moreover, MMP3 gene polymorphisms have been associated with the risk of tendinopathy development." (PMID 41226619, 2025). "Therefore, IL-17-induced increases in MMP3, which encodes for the MMP-3 enzyme that degrades several types of collagens, proteoglycans, as well as other extracellular matrix macromolecules, could contribute to tendinopathy." (PMID 35004653, 2021). "Matrix metalloproteinase 3 (MMP3) belongs to the MMP family and is associated with the pathogenesis of tendinopathy." (PMID 41226619, 2025). "qPCR analysis indicated elevated mRNA levels of TNF-α, IL-6, and MMP3 in the tendinopathy group, indicating the presence of inflammation in tendinopathic tissues." (PMID 39442875, 2025). "IHC staining revealed that NGR1 exhibited a dose-dependent therapeutic effect on tendinopathy, including reducing the expression of the inflammatory cytokine IL-6, downregulating Col3 and MMP3 expression, and upregulating Col1 expression at 5 weeks." (PMID 40697661, 2025). "By intersecting the targets of NGR1 with those associated with tendinopathy, we constructed a PPI network, and the results showed that targets such as IL-6, TNF, AKT1, MMP9, and MMP3 are valuable in assessment." (PMID 40697661, 2025). "In the context of tendinopathy, IL-1β promotes MMP3 expression by activating the MAPK/NF-κB pathway, whereas TGF-β1 exerts anti-degradation effects by suppressing this pathway." (PMID 40918434, 2025).
tendinopathy (continued). "The FBN2 (rs331079), TNC (rs2104772), and MMP3 (rs591058) SNPs were in Hardy–Weinberg equilibrium in the overall participants athletes and in each group (tendinopathy cases and controls)." (PMID 39594135, 2024). "MMP-3 is commonly downregulated in tendinopathy, alongside TIMPs; this asset seems to contribute to clinical condition." (PMID 36830637, 2023). "In the light of current knowledge, well-established factors of susceptibility to tendinopathy are the polymorphic variants of collagen, type I, alpha-1 (COL1A1), collagen, type V, alpha-1 (COL5A1) and matrix metalloproteinase 3 (MMP3) genes." (PMID 35743573, 2022). "Since the content of MMP-3 tended to be decreased in tendinopathy, the plot would indicate publication bias if smaller studies tended to report a decrease of MMP-3 in tendinopathy less often than larger studies did." (PMID 25879758, 2015). "This suggests that MMP3 has a significant role in tendon repair and/or maintenance, and its reduced expression during tendinopathy may disrupt these processes." (PMID 41226619, 2025). "Three MMP3 polymorphisms were selected: rs679620 and rs591058, which have been previously associated with the risk of tendinopathy, and rs520540, which has not been analyzed in this context." (PMID 41226619, 2025). "In addition to MMP-2 and MMP-9, MMP-3 has been found to be dysregulated during tendinopathies, which is inconsistent with its expected role in matrix remodeling." (PMID 38247510, 2024). "We investigated the potential influence of single nucleotide polymorphisms (SNPs) in fibrillin-2 (FBN2), tenascin-C (TNC), and matrix metalloproteinase-3 (MMP3) on the tendon regeneration failure phenotype and impact on the susceptibility to tendinopathy in Brazilian high-performance athletes." (PMID 39594135, 2024). "The TNC-rs2104772-A/MMP3-rs591058-T combination suggests a phenotypic profile of tendon regeneration failure associated with the failure of tendon ECM regeneration, contributing to susceptibility and increased exacerbation of tendinopathy." (PMID 39594135, 2024). "One possible mechanism by which HIF-1 may contribute to tendinopathy is the regulation of MMP3 by its activator TIMP-1." (PMID 38247510, 2024). "Also, core‐resident “tenophage” or “tenoclast” populations have recently been gaining more attention as potential role players in early tendinopathy, especially in combination with increased expression of Tnf‐α, Il‐6, Mmp‐3, and Mmp‐9." (PMID 34494401, 2021). "We did not observe any changes in other matrix proteins or tissue inhibitors of metalloproteinases (TIMP1 and TIMP2) therefore, in the context of tendinopathy, MMP3 may regulate inflammation in addition to influencing matrix remodelling." (PMID 30728384, 2019). "Based on the presented information, it seems that rs679620 has a potential modulatory role in the functioning of MMP3, which is reflected in the clinical phenotype (for example, by increasing the risk of tendinopathy), but the exact mechanism of action is not known and requires further research." (PMID 41226619, 2025). "However, in combination with TNF-α, all three IL-17 cytokines induce similar levels of IL6 and MMP3 mRNA expression, which could make not only IL-17A, but also IL-17F and IL-17AF interesting treatment targets in tendinopathy." (PMID 35004653, 2021). "MMP‐3 and MMP‐9 are strongly up‐regulated in the early phase of tendinopathy promoting inflammation by degrading numerous matrix proteins and releasing danger associated molecular patterns (DAMPs)." (PMID 40855996, 2025). "Given these implications, FBN2 (rs331079), TNC (rs2104772), and MMP3 (rs591058) SNPs may contribute to a more susceptible ECM tendon regeneration failure phenotype, and their interaction with environmental determinants may influence the individual risk for tendinopathy." (PMID 39594135, 2024). "The results of the Mmp3 and Mmp13 were similar, and the CEFFE-MNs group showed less positive staining than the tendinopathy and injection groups." (PMID 37600349, 2023).
tendinopathy (continued). "The expression of the stromelysines MMP3 and MMP10 was significantly decreased in the tendinopathy and chronic rupture groups compared to the acute ruptured tendons." (PMID 29385715, 2018). "This study demonstrates that IL-1β mimics some aspects of tendinopathies with PGE2 induction, MMP expression (mostly MMP1 and MMP3), and increases of type III/I collagen ratio." (PMID 26156631, 2015). "MMP2, MMP3, MMP8, ADAMTS2, ADAMTS4, ADAM12 and collagen type I expression were regulated in a similar manner in tendinopathy compared to the current study." (PMID 23830915, 2013). "The IL-17A-induced expression of downstream inflammatory effectors IL-6, CXCL1 and MMP3 was completely inhibited by secukinumab, suggesting that IL-17A alone and in concert with TNF-α may promote inflammation in tendinopathy." (PMID 39988349, 2025). "Abnormal extracellular matrix (ECM) remodeling was a key characteristic and pathological progress in tendinopathy, and increased COL I, COL III, MMP3 and MMP9 expression as well as decreased COL III/COL I rate and TIMP-1 content were detected in the tendinopathy mice." (PMID 36604715, 2023). "Additionally, the expression of MMP3 and MMP10, the stromelysines, which have an important regulatory function on other MMPs, was significantly decreased in the tendinopathy and chronic rupture groups compared to the acute ruptured tendons." (PMID 29385715, 2018). "Furthermore, the molecular docking results presented the stable and high-affinity binding of NGR1 to TNF-α, IL-6, MMP3, MMP9, and MMP13, indicating that NGR1 may exert its therapeutic effects on tendinopathy by modulating inflammatory responses and cellular and extracellular matrix metabolism." (PMID 40697661, 2025).
diabetes (29 papers, 2013 to 2025). "In univariate analysis, older age, male sex, diabetes duration, GV, diabetic retinopathy, chronic kidney disease, coronary artery disease, peripheral artery disease, and MMP-3 were associated with subclinical CA." (PMID 35011813, 2021). "These include IGFBP-2 and AGER associated with diabetes complications, and MMP-3 associated with extracellular remodeling." (PMID 33053810, 2020). "Hypertension and diabetes were associated with increases in several MMPs/TIMPs, particularly MMP-3 and TIMP-4." (PMID 23967183, 2013). "in vitro experiments indicated that quercetin suppressed the growth and MMP3 expression of thyroid cancer cells under high glucose conditions, thereby alleviating the advancement of TC-diabetes." (PMID 40575254, 2025). "Co-occurrence analysis of the literature was conducted using inflammatory bowel disease, diabetes mellitus, core gene (MMP3), five predicted lncRNAs (TMED10P, NCRNA00092, DIO3OS, CYP2B7P1, CDKN2BAS), and the significantly enriched PPAR pathway as search terms." (PMID 38173213, 2025). "MMP-3 and MMP-8, besides being involved in periodontal pathology, are also associated with cardiovascular pathology and diabetes." (PMID 36830029, 2023). "Blocking MMP-3 expression significantly decreased the rate of diabetes-related complications in many animal models." (PMID 36211828, 2022). "Conversely, Mmp3 gene expression was one of the top elevated gene transcripts in healing bone of animals with diabetes in these microarray analyses." (PMID 35207422, 2022). "In assessment of association between CAD and diabetes in Iranian population the following genes showed significant association: paraoxonase 1, adiponectin, eNOS, CETP, AT1R, resistin, MMP-3, BChE K, Apo E, ACE." (PMID 26587547, 2015). "Proliferative retinopathy (n = 146) was associated with higher levels of MMP-2 [0.71 (0.45; 0.96)], MMP-3 [0.49 (0.28; 0.70)], MMP-10 [0.39 (0.11; 0.66)] and TIMP-1 [0.54 (0.28; 0.81)] after adjustment for age, sex, duration of diabetes and HbA1c (Model 1)." (PMID 25848912, 2015). "In summary, quercetin may suppress the progression of TC-diabetes by inhibiting the proliferation of thyroid cancer cells and the expression of MMP3." (PMID 40575254, 2025). "Additionally, a correlation between MMP-3 and MMP-14 expression was observed, suggesting that MMP-3 might influence MMP-14 activity in the progression of periodontal disease linked to diabetes." (PMID 40075856, 2025). "However, MMP-3 levels the diabetes + β-anhydroicaritin group and diabetes + urate group were significantly higher compared with those in the diabetes group (P<0.05), and those in the diabetes + β-anhydroicaritin group were lower compared with those in the diabetes + urate group (P<0.01)." (PMID 25847066, 2015). "High levels of MMP-2, MMP-3, MMP-8 and MMP-9 have been found in the epithelium and stroma of melted and perforated corneas after topical NSAID use and in patients with diabetes." (PMID 38528481, 2024). "Specifically, in the SBECD + OTX + CHR treatment group, TIMP-1, MMP-2, MMP-3, and MMP-9 expressions dropped approximately by about 29.04, 15.12, 58.77, and 19.41 times, respectively, compared to the diabetes group." (PMID 38169923, 2023). "The serum levels of MMP3 were positively related to the male gender and hypertension, while MMP9 was positively related to the age and the male gender of patients, diabetes, and the treatment with steroids." (PMID 35075175, 2022). "After confirming that MMP-3 was closely related to survival and diabetes in PDA models, we next analyzed the role of MMP-3 in PDA gemcitabine resistance and invasion." (PMID 36211828, 2022). "Our present study also indicated a correlation between the level of MMP-3 and MMP-9 and the duration of diabetes." (PMID 36362386, 2022). "Patients with diabetes, as a whole group, demonstrated increased serum levels of L-citrulline (p = 0.006), MMP-2 (p = 0.0002), and MMP-3 (p = 0.008) as compared to controls." (PMID 35011813, 2021).
diabetes (continued). "Patients with comorbidities such as hypertension, obesity, and diabetes had elevated DPPIV, MMP-8, and TIMP-4 levels, and reduced MMP-3 and TIMP-2 levels, indicating a link between these markers and the exacerbating effects of comorbidities on COVID-19 outcomes." (PMID 40557167, 2025). "In addition, we were interested in the level of MMP-3 and MMP-9 in patients with DM2 with EBV infection with different durations of diabetes and body mass index (BMI)." (PMID 36362386, 2022). "Among the MMPs examined, MMP-1, MMP-2, MMP-3, and MMP-7 were detected in all vitreous samples from patients with PDR and control patients without diabetes." (PMID 24392031, 2013). "Moreover, the significant alteration in levels of MMP1, MMP3, MMP11, CHI3L1 and VEGF-A in non-diabetic fibroblasts between day 3 and day 7 after the wound were all abolished in diabetic M1 fibroblasts, and their expression levels were also significantly lower in diabetes." (PMID 38270651, 2024).
disc degeneration (28 papers, 2009 to 2025). "In a North Iranian population, the homozygous variant (CC) of the polymorphism rs632478 in MMP3 resulted in 5-fold significant increased risk for disc degeneration relative to the AA variant." (PMID 30464887, 2018). "The association of MMP3 SNP rs72520913 with severe degeneration is in agreement with previously reported associations with disc degeneration." (PMID 23522322, 2013). "Recently, MMP‐3 gene polymorphisms were widely evaluated in lumbar disk degeneration (LDD)." (PMID 32157746, 2020). "Since metalloproteinases, particularly members of the ADAMTS and matrix metalloproteinase (MMP) families, are major contributors to aggrecan degradation and loss in disc degeneration, MMP-3, ADAMTS-4 and ADAMTS-5 message levels were also examined, as their suppression is essential for disc repair." (PMID 21787415, 2011). "MMP3 can degrade extracellular matrix components, including various types of collagen, and is believed to promote disc degeneration." (PMID 39015652, 2024). "Noteworthy, in a preclinical study published in 2022, it was shown that local delivery of bevacizumab alleviates disc degeneration and MMP3 production." (PMID 37220462, 2023). "For example, MMP-3 has an optimum pH window between 5.5 and 6.5 and is particularly active in disc degeneration where this condition is verified." (PMID 36830637, 2023). "As a substance that destroys articular cartilage and intervertebral disc matrix, MMP3 is involved in disc degeneration, especially during the matrix degradation stage." (PMID 33505586, 2021). "Both of them are involved in the process of disc degeneration, with MMP-3 up-regulated and ADAMTS-10 down-regulated in degenerative intervertebral disc tissue." (PMID 32210816, 2020). "Histological examinations and aggrecan, Col1A1, Col2A1 and matrix metalloprotease (MMP)-3 mRNA expression confirmed the disc degeneration, supporting the imaging results." (PMID 26924131, 2016). "MMP-3, which plays a major role in disc degeneration, has a broad substrate specificity, and has been shown to degrade proteoglycans, lamin, Fn, gelatins, and collagen types II, III, IV, and V." (PMID 26921206, 2016). "Upregulated genes with known roles in disc degeneration included interleukin-6 (Il-6), matrix metallopeptidase 3 (Mmp3), and a disintegrin and metalloproteinase with thrombospondin motifs 5 (Adamts5)." (PMID 24171898, 2013). "We analyzed matrix metalloproteinase-3 (MMP-3) expression which plays a major role in the disc degeneration process using Actb and combination of Hprt1 and CycA." (PMID 21615931, 2011). "A recent study even specified that the biochemical mediators of inflammation and tissue degradation including MMP-3, IL-1β and inducible nitric oxide synthase were significantly increased along with the disc degeneration that was induced by needle puncture." (PMID 19912653, 2009). "In addition, factors such as IL-1β, MAPK14, MMP9, and MMP3 can contribute to inflammation and matrix degradation, potentially further interacting with Wnt signaling to exacerbate disc degeneration." (PMID 39623712, 2025). "ADAMTS-5 may be the main enzyme involved in matrix breakdown during the acute phase of puncture injury-induced disc degeneration and septic discitis, whereas in the case of P. acnes infection MMP-3 was predominant." (PMID 35587595, 2022). "In the current study, MMP-3 was secreted from mIVDs via PAR1 in response to treatment with thrombin suggesting that MMP-3 may be involved in disc degeneration via proteoglycan degeneration and changes in the population of NP cells." (PMID 30054581, 2018). "We demonstrated that MMP3 expression was decreased and COL II synthesis was promoted, when VEGF expression was inhibited by bevacizumab, thereby improving the degree of disc degeneration." (PMID 36213074, 2022). "Three, recent studies suggest that expression of MMP-3, MMP-9, and MMP-13 is increased in degenerative disc disease." (PMID 30704538, 2019).
disc degeneration (continued). "We investigated MMP-3 immunopositivity as representative of MMPs, judging from published evidence highlighting the significant importance of MMP-3 in disc degeneration." (PMID 22394620, 2012). "The p38 MAPK can affect the expression of MMP1, MMP3, MMP13, IL-6, IL-8, COX-2, iNOS, and TGF-β, as well as control the expression of anabolic and anti-catabolic genes such as proteoglycans, collagen I protein and collagen II, leading to disc degeneration." (PMID 38313000, 2023). "Furthermore, they showed differences in overexpression of selective inflammatory and catabolic proteins (p<0.0001) similar to those found in human NP cells of different disc degeneration grades, such as IL-1β, TNF-α, ADAMTS-4, ADAMTS-5 and MMP-3." (PMID 31751427, 2019).